KDM5B (lysine demethylase 5B)
Description:
Histone demethylase that demethylates 'Lys-4' of histone H3, thereby playing a central role in histone code. Does not demethylate histone H3 'Lys-9' or H3 'Lys-27'. Demethylates trimethylated, dimethylated and monomethylated H3 'Lys-4'. Acts as a transcriptional corepressor for FOXG1B and PAX9. Favors the proliferation of breast cancer cells by repressing tumor suppressor genes such as BRCA1 and HOXA5. In contrast, may act as a tumor suppressor for melanoma. Represses the CLOCK-BMAL1 heterodimer-mediated transcriptional activation of the core clock component PER2 (By similarity).
Synonyms: CT31; RBP2-H1; JARID1B; PLU1; RBBP2H1A; PLU-1; PPP1R98; MRT65; PUT1
Tractability: Small molecule: a structure with a bound ligand is known; a high-quality ligand is known. PROTAC: UniProt records ubiquitination sites on it; ubiquitination databases record sites on it; its protein half-life has been measured; a small molecule that binds it is known.
Target class: Epigenetic regulator; Jumonji domain-containing; Eraser; Lysine demethylase
Chemical probes: GSK-J1, GSK-J4 (high quality)
Gene: Protein-coding gene on chromosome 1 (202,724,495 to 202,808,487, reverse strand). Ensembl gene ENSG00000117139.
Subcellular location: Nucleus
Subcellular location (Human Protein Atlas): Nucleoplasm; Cytosol
Pathways (Reactome):
Chromatin organization: HDMs demethylate histones
Developmental Biology: Chromatin modifications during the maternal to zygotic transition (MZT)
Gene expression (Transcription): TFAP2 (AP-2) family regulates transcription of cell cycle factors
Gene Ontology:
Molecular function: DNA binding; histone binding; histone H3K4 demethylase activity; histone H3K4me/H3K4me2/H3K4me3 demethylase activity; nucleic acid binding; protein binding; sequence-specific double-stranded DNA binding; transcription corepressor activity; zinc ion binding; histone demethylase activity
Biological process: negative regulation of DNA-templated transcription; regulation of DNA-templated transcription; cellular response to fibroblast growth factor stimulus; chromatin remodeling; lens fiber cell differentiation; response to fungicide
Cellular component: nucleoplasm; nucleus; chromatin; ribonucleoprotein complex
Genetic constraint (gnomAD): Loss-of-function variants: 120 observed, 162.83 expected, observed/expected ratio (o/e) 0.74, 90% interval 0.63 to 0.86. The upper end of that interval is the gene's LOEUF score, 0.86, which puts it in group 3 of 6, group 1 being the genes least tolerant of losing a copy. Missense variants: 1,614 observed, 1,729.3 expected, observed/expected ratio (o/e) 0.93, 90% interval 0.89 to 0.97. Synonymous variants: 588 observed, 638.48 expected, observed/expected ratio (o/e) 0.92, 90% interval 0.86 to 0.99.
Gene-disease validity (ClinGen):
ClinGen rates the evidence that KDM5B causes each of these diseases.
intellectual disability (autosomal recessive): Moderate.
Homologues: Orthologues: chimpanzee KDM5B (99% identical), macaque KDM5B (99% identical), guinea pig KDM5B (95% identical), mouse Kdm5b (94% identical), rat Kdm5b (94% identical), pig KDM5B (94% identical), dog KDM5B (93% identical), rabbit KDM5B (93% identical), tropical clawed frog kdm5b (70% identical), zebrafish kdm5bb (62% identical), zebrafish kdm5ba (62% identical), Drosophila melanogaster Kdm5 (43% identical), and 1 more. Paralogues in human: KDM5A (52% identical), KDM5C (46% identical), KDM5D (45% identical), KDM4A (14% identical), KDM4C (14% identical), KDM4B (13% identical), JARID2 (13% identical), KDM4D (9% identical), KDM4F (8% identical), KDM4E (8% identical).
Diseases named in the same sentence as KDM5B in open-access papers:
KDM5B is named in the same sentence as 147 diseases in open-access papers, as found by Europe PMC text mining. Sharing a sentence is not in itself a finding about the gene and the disease. The quoted sentences say what the papers report.
melanoma (111 papers, 2011 to 2025). A malignant, usually aggressive tumor composed of atypical, neoplastic melanocytes. "KDM5B is a H3K4 demethylase that has been implicated in melanoma resistance to targeted BRAF inhibitor therapies." (PMID 35515106, 2022). "High KDM5B expression in melanoma is significantly associated with poor patient survival, while other KDM5 family members lack such an association." (PMID 35650266, 2022). "The supporting effects of KDM5B on chemoresistance have been implicated in gastric cancer, melanoma, as well as endometrial carcinoma." (PMID 35333349, 2022). "High KDM5B expression was associated with a slow cycling population of melanoma cells that prolonged growth and self-renewal." (PMID 34220955, 2021). "Linking epigenetics to tumor heterogeneity, upon exposure to targeted therapies, elevated KDM5B expression shifts melanoma cells to a more drug-tolerant CD34- state while KDM5B loss shifts melanoma cells to a more sensitive CD34+ state." (PMID 32042336, 2020). "KDM5B had been implicated as a tumor suppressor in malignant melanoma as its expression level was downregulated and it inhibited cell proliferation in an Rb-dependent manner." (PMID 27974677, 2017). "The histone demethylase KDM5B is highly expressed in many cancers including melanoma cell lines and patient tumours and causes a slowing of the cell cycle which promotes resistance to chemotherapeutic drugs." (PMID 28806732, 2017). "Thus, high KDM5B expression is associated with a slow-cycling differentiated phenotype that allows melanoma cells to cope with stress and survive under treatment." (PMID 35406721, 2022). "Furthermore, JARID1B (KDM5B) is an H3K4me3 histone demethylase implicated in the regulation of melanoma phenotype and metabolome reprogramming." (PMID 35406721, 2022). "We found that KDM1B and KDM5B exhibited the highest mutation rates in melanoma in the TCGA dataset." (PMID 34220955, 2021). "Soon after, another study on melanoma reported the identification of a small subpopulation of slow-cycling cancer cells using KDM5B/Jarid1B as a biomarker." (PMID 38893049, 2024). "The second gene most related to TFAP2A was KDM5B, a histone demethylase which has been proven essential for immune evasion in melanoma." (PMID 38265973, 2024). "Deletion of Kdm5b in melanoma cells extends the survival of tumor-bearing mice and increases CD8+ T cell infiltration into the TME." (PMID 39133578, 2024). "Reexpression of either wild-type KDM5B or catalytically inactive KDM5B in Kdm5b–/– melanoma cells rescues this phenotype." (PMID 39133578, 2024). "The contribution of SETDB1 to immune evasion was also evidenced in melanoma and colorectal mouse cell lines, however via interaction with KDM5B (lysine-specific demethylase 5B), a histone demethylase targeting H3K4me3." (PMID 39519018, 2024). "In melanoma, KDM5B was shown to induce an anti-tumor immune response and was required for immune evasion of cells in an in vivo model." (PMID 35899196, 2022). "Based on these findings, early studies suggested the tumor-suppressive roles of KDM5B in melanoma; however, later studies revealed its oncogenic functions in melanoma." (PMID 35805040, 2022). "On the other hand, enforced KDM5B expression limits tumor plasticity and heterogeneity, resulting in the elimination of melanoma cells by promoting melanocytic differentiation." (PMID 35805040, 2022). "Melanoma cells were shown to be composed of heterogeneous cancer cells that, when expressing high levels of KDM5B, are resistant to therapy such as MAPK inhibition, giving rise to tumor repopulation after initial therapy." (PMID 35899196, 2022).
melanoma (continued). "For instance, KDM5B gene elimination sensitizes melanoma cells to BRAF blockage, despite the fact that survived cells display the IDTC phenotype." (PMID 36224606, 2022). "Accordingly, KDM5B knockout sensitized treatment-resistant YUMM1.7 melanoma cells to in vivo anti-PD-1 treatment through boosted CD8+ T cell activity." (PMID 36497341, 2022). "BRAFi induces the enrichment of drug-resistant CD34− melanoma cells, upregulation of KDM5B, and global reduction in H3K4me3." (PMID 36497341, 2022). "Melanoma cells with high expression of the H3K4 demethylase KDM5B (JARID1B) rest in a slow-cycling, yet reversible persister state." (PMID 35650266, 2022). "Next, we tested how melanoma cell populations behaved, when the KDM5B expression spectrum was constantly directed to a higher level without the chance to dynamically revert to normal heterogeneity." (PMID 35650266, 2022). "Our data suggest that KDM5B directs the transcriptional identity of melanoma cells from undifferentiated towards melanocytic lineage differentiation." (PMID 35650266, 2022). "For example, KDM5B suppressed antitumor immunity and mediated immune evasion in melanoma by recruiting SETDB1 (SET domain bifurcated histone lysine methyltransferase 1) to silence retroelements." (PMID 36481938, 2022). "KDM5B upregulation following BRAFi treatment decreases H3K4me3 levels and triggers the conversion of melanoma cells from drug-sensitive CD34+ to drug-resistant CD34- cell states." (PMID 36497341, 2022). "KDM5B expression in melanoma is usually heterogeneously distributed, whereas benign melanocytic nevi express KDM5B at high levels across the majority of cells (Fig. 1a15)." (PMID 35650266, 2022). "This suggests that slow-cycling KDM5Bhigh persister cells represent a transient source for tumor repopulation, but longevity of melanoma requires a dynamic KDM5B tumor composition." (PMID 35650266, 2022). "Longitudinal treatment of melanoma cells with the protein synthesis inhibitor cycloheximide revealed a steady decrease of KDM5B protein yielding a 79 and 98% decrease after 24 and 72 h, respectively." (PMID 35650266, 2022). "We first demonstrated by DNA content cell cycle analyses that enforced KDM5B expression over 72 h dose-dependently induces cell cycle delay across various genetically different melanoma cell lines." (PMID 35650266, 2022). "KDM5A is overexpressed in several cancers including acute myeloid leukemia and lung cancers, KDM5B in breast cancer and melanoma, and KDM5C in prostate cancers, as well as metastatic breast and gastric cancers." (PMID 34184733, 2021). "Recent research revealed that expression of KDM5B follows a highly dynamic equilibrium across melanoma cells." (PMID 34591417, 2021). "KDM5B targets are known to drive a slow cycling state of melanoma after treatment-induced de-differentiation." (PMID 34591417, 2021). "Interestingly, KDM5B overexpression has been associated with chemotherapy resistance in epithelial ovarian cancer, with the development of Glioma, and with the presence of a subpopulation of slow-cycling cells involved in long-term tumour maintenance in melanoma." (PMID 34184733, 2021). "Accordingly, KDM5B appears to represents a checkpoint for coordinating differentiation of melanoma cells via transcriptional reprograming, and cell cycle delay." (PMID 34591417, 2021). "On the other hand, potential tumor-suppressive functions of KDM5B have also been documented in some cases of melanoma and subtypes of breast cancer." (PMID 33245716, 2020). "The relevance of KDM5B in chemo-resistance was confirmed when KDM5B depletion led to the increased sensitivity of melanocytes to anti-melanoma treatment." (PMID 32751840, 2020). "Differential expression of KDM5B can thus be used to identify a small subpopulation of melanoma cells characterized by distinct bioenergetics that are resistant to various drugs." (PMID 31623133, 2019).
melanoma (continued). "Melanoma cells expressing high levels of KDM5B cycled slowly and possessed a high self‐renewal potential, while knockdown of KDM5B resulted in a reduction in tumorigenic activity." (PMID 31776402, 2019). "One such enzyme, H3K4 demethylase JARID1B (PLU-1, KDM5B), plays a role in the development of melanoma, and regulates gene transcription and cell differentiation." (PMID 30466474, 2018). "Previously it has been shown that stable knockout of KDM5B reversed the slow cycling population in melanoma cells." (PMID 29492189, 2018). "Knockdown of KDM5B led to an exhaustion of tumorigenesis in series transplantation experiments, indicating that KDM5B regulated stem cell-like properties in melanoma cells in a dynamic fashion." (PMID 27974677, 2017). "In contrast, KDM5B was also reported to have oncogenic functions to promote melanoma maintenance and metastatic progression in immunodeficient mice." (PMID 27974677, 2017). "Since it is known that stem-like cells divide with lowest rates, cells of the identified KDM5B subgroup are interesting candidates for stem-like melanoma cells." (PMID 27903987, 2017). "In highly metastatic melanomas, re-expression of KDM5B can modulate retinoblastoma protein (pRb)-hypophosphorylation selectively at Ser795 to reveal tumor-suppressive function." (PMID 27974677, 2017). "Inactivating mutations in SWI/SNF family member genes (ARID1A, ARID1B, ARID2, and SMARCA4) and in members of another chromatin-remodeling family referred to as the poly comb complex (EZH2, BMI1, and JARID1B/KDM5B) have been found altered in melanoma." (PMID 26322273, 2015). "For example KDM5B (Histone demethylase JARID1B) is overexpressed in many cancers including breast, prostate, and lung cancer as well as melanoma where it confers resistance to apoptotic stimuli such as cisplatin and vemurafenib." (PMID 25527049, 2014). "Through the use of H3K4 demethylase Jarid1b (Kdm5b/Plu-1/Rbp2-h1) as a biomarker, a small subpopulation of tumor-initiating melanoma cells was isolated." (PMID 24649241, 2013). "Using esophageal cancer cells, we investigated the functional roles of the H3K4 demethylase Jumonji/Arid1b (Jarid1b) (Kdm5b/Plu-1/Rbp2-h1), an epigenetic factor that is required for continuous cell growth in melanoma." (PMID 24649241, 2013). "In melanoma, KDM5B recruits SETDB1 to repress its targets and further promotes immune evasion." (PMID 38317200, 2024). "Recently, it has been proposed that the relative abundance of different KDM5B isoforms may contribute to tumor progression in melanoma." (PMID 36697763, 2023). "Due to the pronounced nuclear enrichment of KDM5B seen across the majority of melanoma cells upon Cpd1 treatment, we hypothesized that Cpd1 might affect the natural homeostasis of KDM5B protein as a potential mode of action." (PMID 35650266, 2022). "The authors of a recent study identified an immune evasion function driven by KDM5B in melanoma." (PMID 35805040, 2022). "For example, treatment of melanoma cells with different chemotherapeutics promotes the enrichment of slow-cycling long-term tumor-maintaining cells expressing the H3K4-demethylase JARID1B/KDM5B/PLU-1." (PMID 35158815, 2022). "In melanoma, KDM5B expression progressively decreases with intratumoral heterogeneity." (PMID 35805040, 2022). "Our experiments suggest so far that exogenous expression of KDM5B can direct melanoma towards a slow-cycling tumor phenotype across the majority of tumor cells, where different molecular mechanisms might cooperate to prevent cell proliferation." (PMID 35650266, 2022). "KDM5B regulates transitions between melanoma-propagating cells with varying drug sensitivities that could potentially be exploited therapeutically." (PMID 36497341, 2022). "Our midbody analysis estimates that a considerable fraction of KDM5B-enforced melanoma cells needs prolonged time to complete cell abscission, which might contribute the observed overall cell cycle delay." (PMID 35650266, 2022).
melanoma (continued). "Finally, although mechanistically unclear, SETDB1 and KDM5B demonstrate pleiotropic effects in melanoma targeted therapy and immunotherapy which demand deeper mechanistic exploration." (PMID 36497341, 2022). "In melanoma, where slow-cycling cancer cells show high KDM5B expression, RB/KDM5B interactions may be involved in tumor suppression." (PMID 35899196, 2022). "In contrast, pre-treatment of melanoma cells with Cpd1 for only 3 days before seeding onto soft agar was not sufficient to reduce the number of formed colonies again suggesting spontaneous reversibility of the KDM5B phenotype under normal conditions." (PMID 35650266, 2022). "This suggested a correlation between KDM5B DNA-binding motifs and H3K4me3 chromatin marks across a number of cytokinesis genes (breast cancer and melanoma cell lines) and melanocytic differentiation genes (melanoma cell lines)." (PMID 35650266, 2022). "The observed KDM5B-dependent cell state reprograming not only confirms commitment to melanocytic differentiation, it could also sensitize melanoma cells for secondary phenotype-specific drugs." (PMID 35650266, 2022). "As KDM5B has been reported to guide developmental processes in a highly conserved fashion, we asked if enforced KDM5B expression could affect the differentiation state of melanoma cells." (PMID 35650266, 2022). "Applying SLF′-thalidomide to FKBP2-tagged KDM5B in WM3734 melanoma cells, we could demonstrate that KDM5B protein is quickly proteosomally degraded in an E3 ubiquitin ligase-dependent manner." (PMID 35650266, 2022). "The study suggests that KDM5B may have an important role in the maintenance of stem like progenitors that seed tumor progression and metastasis in melanoma." (PMID 34220955, 2021). "Importantly, inhibition of mitochondrial respiration blocks the emergence of the KDM5B(high) subpopulation and sensitized melanoma cells to therapy." (PMID 32042336, 2020). "Also in melanoma, the expression of the histone demethylase JARID1B (also known as KDM5B) defines a population of slow-cycling cells with tumourigenic potential, i.e. CSCs." (PMID 29991569, 2018). "In addition to breast cancer and melanoma, overexpression of KDM5B had also been described in bladder cancer and lung cancer." (PMID 27974677, 2017). "Therefore, KDM5B seemed to have a dual role during melanoma progression, initially exhibiting anti-proliferative activity but progressively becoming necessary for continuous tumor growth and maintenance." (PMID 27974677, 2017). "JARID1B, also known as the PLU1 or KDM5B, is a H3K4me3 histone demethylase that is overexpressed in many cancer types including breast, prostate, bladder, and lung cancers, as well as associated with tumor progression of melanoma." (PMID 25951238, 2015). "KDM5B, also known as JARID1B, was required to maintain tumorigeneic activity in melanoma cells, and the knockdown of KDM5B may trigger apoptosis and reduces proliferation in bladder and lung cancers." (PMID 25889623, 2015). "KDM4A and KDM5B can be considered proto-oncogenes, and targeting these demethylases could potentially result in tumor suppression, which makes them attractive therapeutic targets in melanoma." (PMID 40075679, 2025). "Also, melanoma cells that had previously developed resistance to MAPK inhibition responded to chemical enforcement of the KDM5B phenotype supporting the observation that chronically drug-resistant melanoma cell populations re-establish normal KDM5B heterogeneity after initial KDM5B enrichment." (PMID 35650266, 2022). "Interestingly, KDM5B overexpression reprogrammed melanoma cells to a CD34−, more drug-tolerant, phenotype, while KDM5B loss shifted melanoma cells to a more BRAFi-responsive CD34+ state, potentiating the pivotal role of KDM5A in modulating intratumoral heterogeneity in CM." (PMID 34575678, 2021). "Interestingly, it is evident that, in melanoma cells, KDM5B expression is dynamically regulated." (PMID 32751840, 2020).